ST6GAL1 (ST6 beta-galactoside alpha-2,6-sialyltransferase 1)
Diseases named in the same sentence as ST6GAL1 in open-access papers (continued):
Sharing a sentence is not in itself a finding about the gene and the disease.
Arthritis (6 papers, 2016 to 2024). Inflammation of a joint. "Inhibition of ST6GAL1 and α2,6 sialylation was also associated with a proinflammatory state in arthritis." (PMID 36345944, 2022). "ST6GAL1 inhibition increases lung inflammation, promotes arthritis development, and suppresses ulcerative colitis development." (PMID 39354345, 2024). "A recent study in experimental arthritis displayed that phytoestrogen treatment enhanced sialyltransferase, St6gal1 mRNA expression in the splenic tissue." (PMID 37766692, 2023). "In particular, st6gal1 gene-depleted mice produced low α-2,6-sialylated IgG anti-collagen antibodies that resulted in exacerbated joint inflammation and high arthritis scores." (PMID 37629178, 2023). "The activity of recombinant human galactosyltransferase B4GALT1 and ST6Gal1 on a single Fc fragment of IgG1 attenuated inflammation in a K/BxN arthritis model." (PMID 35370997, 2022). "Therefore, deficient ST6Gal1 expression in activated B cells did not cause severe defects in B-cell pathways for arthritis-associated IgG production." (PMID 27046227, 2016). "Therefore, not only is the content of α-2,6-SIA in autoantibodies important for pathogenesis of human RA and CIA in mice, but ST6Gal1 and Neu1 capable of producing and removing α-2,6-SIA are also important for collagen-induced arthritis in mouse and human fibroblasts." (PMID 37629178, 2023).
glioblastoma (6 papers, 2019 to 2025). The most malignant astrocytic tumor (WHO grade IV). "GD3 has been identified as a marker for glioblastoma stem cells (GSCs) and overexpression of ST6Gal1 and GD3 synthase (GD3S) has been shown to enhance CSC properties by stabilizing oncogenic signaling pathways like c-MET signaling." (PMID 39628991, 2024). "Additionally in glioblastoma, ST6Gal1-mediated α2,6-sialylation of crucial receptors such as EGFR and TNFR1 has been shown to enhance tumor-initiating cell (TIC) properties to foster increased self-renewal, therapy resistance, and invasion." (PMID 39628991, 2024). "We demonstrate a potentially novel, protumorigenic role for α2,6 sialylation and ST6GAL1 in the deadly brain tumor glioblastoma (GBM)." (PMID 36345944, 2022).
melanoma (6 papers, 2016 to 2022). A malignant, usually aggressive tumor composed of atypical, neoplastic melanocytes. "Utilizing ST6Gal1 null mice inoculated with B16-F0 melanoma tumors, it was revealed that α2,6 sialylation was high in tumors sensitive to anti-VEGF monoclonal antibody treatment, and ST6Gal1 knockout also led to protection against anti-VEGF treatment." (PMID 36106023, 2022). "Chronic elevation of circulatory ST6Gal-1 by subcutaneous implantation of a B16 melanoma engineered to release ST6Gal-1 partially alleviated the sterile agent induced acute airway." (PMID 30778346, 2019). "Another report provided insight into the role of ST6GAL1 in melanoma." (PMID 34440905, 2021). "We recently showed that subcutaneous implantation of localized B16 melanoma engineered to overexpress ST6Gal-1 could partially alleviate neutrophilic airway inflammation when challenged intratracheally with LPS in mice." (PMID 30778346, 2019). "Indeed, the depletion of sialylated glycoconjugates by either enzymatic desialylation or silencing of ST6GAL1 decreased the adhesion on both extracellular matrix (ECM) and basement membrane (BM) components and reduced invasiveness of murine B16 melanoma cells." (PMID 34440905, 2021).
psoriasis (6 papers, 2022 to 2025). An autoimmune condition characterized by red, well-delineated plaques with silvery scales that are usually on the extensor surfaces and scalp. "Given that others have associated ST6GAL1 with psoriasis in an Asian population, these data support a link between these syndromes and an underlying defect in the inflammatory pathway." (PMID 35467766, 2022). "We also sought to confirm an association between ST6GAL1 and T2D, and understand their interrelationship with HFS by studying biomarkers of inflammation and psoriasis using data from the UK Biobank." (PMID 35467766, 2022). "This may suggest that the expression of the two enzymes may be regulated differently with the involvement of either both C1GALT1 and ST6GAL1 or exclusively ST6GAL1 for AD and psoriasis, respectively." (PMID 35784319, 2022). "Furthermore, a comparison of the levels of the enzymes in AD vs psoriatic epidermis suggested a degree of disease-specificity, with B4GALT1, FUT4 and ST6GAL1 found expressed at levels significantly higher than in psoriasis." (PMID 35784319, 2022).
COVID-19 (5 papers, 2021 to 2024). A disease caused by infection with severe acute respiratory syndrome coronavirus 2. "Hub proteins for post-COVID-19 individuals included cytastatin 3 (CST3), Notch homolog 1, translocation-associated (NOTCH1), complement factor H-related 5 (CFHR5), and ST6 beta-galactoside alpha-2,6-sialyltransferase 1 (ST6GAL1)." (PMID 36405747, 2022). "When we examined the PBMC sialyltransferase mRNA expression data, we did not observe significant changes in the ST6GAL1 mRNA levels between severe and nonsevere COVID-19 cohorts." (PMID 38195739, 2024). "In addition, the transcriptomic level of ST6GAL1 and ST3GAL4 also increased in the BMMCs from COVID-19 patients." (PMID 34349096, 2021). "Interestingly, the ST6GAL1 did not significantly differ between COVID-19 severity suggesting that a portion of the increased sialylation on IgM is due to the α−2,3 sialyltransferase ST3GAL4." (PMID 37398192, 2023).
leukemia (5 papers, 2016 to 2022). A malignant (clonal) hematologic disorder, involving hematopoietic stem cells and characterized by the presence of primitive or atypical myeloid or lymphoid cells in the bone marrow and the blood. "Compared to mice transplanted with leukemia cells expressing original ST6Gal1 levels, increased ST6Gal1 expression was associated with significantly reduced survival." (PMID 35371997, 2022). "Also, compared to mice transplanted with leukemia cells expressing original ST6Gal1 levels, increased ST6Gal1 expression was associated with significantly reduced survival." (PMID 35371997, 2022). "Interestingly, we found increased levels of sialylated N-glycans, including α2-6 sialic acid-linked glycoconjugates, in the leukemia samples despite a downregulation of ST6GAL1 on a transcript level." (PMID 35371997, 2022). "Based on bioluminescence, mice transplanted with high ST6Gal1-expressing BCP-ALL cells showed a more rapid leukemia expansion compared to the controls and more rapid body weight loss." (PMID 35371997, 2022). "Upon vincristine discontinuation, relapse was detected in both groups, but mice transplanted with ST6Gal1 overexpressing BCP-ALL cells had an increased leukemia burden and shorter survival than controls." (PMID 35371997, 2022). "When used as a Western blot probe, SNA detects many glycoproteins, and/or different glycoforms of the same protein in BCP-ALL cell lines indicating that ST6Gal1 can sialylate numerous substrates in this type of leukemia." (PMID 35371997, 2022). "Nude mice model of ST6GAL1-driven leukemia tumor growth was also assessed." (PMID 31096997, 2019). "For example, based on the reported suppression of myeloid development by ST6Gal1 in multiple myeloma, it is possible that ST6Gal1 overexpressing BCP-ALL cells suppressed myeloid development in the bone marrow, which, in turn, could promote leukemia proliferation." (PMID 35371997, 2022).
lung carcinoma (5 papers, 2021 to 2025). "A single-nucleotide polymorphisms research directly implicated that the ST6GAL1 gene was associated with lung carcinoma risk in the Chinese Han population." (PMID 34818961, 2021). "In addition, α2,6-sialylation by ST6GAL1 has been linked to lung cancer progression by mediating tumor invasiveness and protecting cancer cells through hypoxia inducible factor (HIF)-1α signaling." (PMID 34290711, 2021). "Increases in ST6GAL1 gene copy number are observed in many different types of malignancies, including 30 to 40% of lung cancer patients." (PMID 39260693, 2024). "Interestingly, ST6GAL1 has been shown to regulate Notch1, Hes1, matrix metalloproteinases (MMPs) and vascular endothelial growth factor (VEGF) in lung cancer and altered α2-6 sialylation has been linked to lung cancer progression." (PMID 34290711, 2021). "Parallel observations from Chinese lung cancer cohorts included enriched TNF-α pathway activity and higher plasma TNF levels, while elevated IL-10/CCL2 in elderly patients and ST6GAL1 in high-grade irAEs further highlight shared inflammatory axes." (PMID 40722787, 2025). "According to a recent study, ST6GAL1 levels dramatically rose, whereas ST3GAL1, ST6GALNAC3, and ST8SIA6 levels were noticeably decreased in lung cancer tissues and cells." (PMID 36547200, 2022).
metastatic tumors (5 papers, 2016 to 2024). "The mRNA data from the TCGA database analyzed in our study also support the associations between ST6GAL1 mRNA expression and metastatic tumors, lymph node metastasis status, clinical stage, and shorter overall survival in thyroid cancers." (PMID 38003522, 2023). "We found that primary and metastatic tumors in the TCGA cohort had significantly higher levels of ST6GAL1 mRNA compared to healthy controls (p = 0.008)." (PMID 38003522, 2023). "TCGA data also showed significantly higher ST6GAL1 mRNA levels in primary and metastatic tumors compared to healthy controls." (PMID 38003522, 2023). "TCGA data revealed increased ST6GAL1 mRNA levels in both primary and metastatic tumors versus controls." (PMID 38003522, 2023). "Corresponding to the results that the two Neu5Ac-α-2,6- residues were necessary for these CSC HPs binding, the enzymes possibly catalyzing the sialylation reactions, ST6Gal1 and ST6GalNAc5, were found to be highly expressed in malignant and metastatic tumors and corresponding to a worse prognosis." (PMID 29755667, 2018).
ovarian tumor (5 papers, 2008 to 2022). "ST6GAL1 upregulation has been associated with numerous types of cancer including pancreatic, prostate, breast and ovarian tumors." (PMID 36297573, 2022). "Furthermore, by knocking down β-galactoside α2-6-sialyltransferase ST6Gal-1, which catalyzes the addition of sialic acid to galactose, ovarian tumor cells gained cisplatin resistance." (PMID 35743163, 2022).
atherosclerosis (4 papers, 2019 to 2025). A disease characterized by the build-up of fatty material and calcium deposition in the arterial wall resulting in partial or complete occlusion of the arterial lumen. "Another gene associated with atherosclerosis development in BD patients is ST6GAL1." (PMID 41141090, 2025). "CX3CR1 and ST6GAL1 genes have been identified in association with atherosclerosis." (PMID 41141090, 2025). "ST6Gal‐1 is found at decreased levels in atherosclerosis development, this suggests a role for BACE1 in its regulation." (PMID 35119166, 2022). "A previous study had shown that the overexpression of ST6GAL1 strongly inhibits monocyte-transendothelial migration, suggesting that ST6GAL1 could be a potential target for atherosclerosis prevention and treatment." (PMID 39290304, 2024). "BACE1 cleavage of ST6Gal‐1, a protein involved in the terminal step of N‐glycan biosynthesis of glycoproteins, contributes to preventing monocyte transendothelial migration, a pivotal mechanism in the initial stages of atherosclerosis." (PMID 35119166, 2022).
autoimmune disease (4 papers, 2019 to 2022). A disorder resulting from loss of function or tissue destruction of an organ or multiple organs, arising from humoral or cellular immune responses of the individual to their own tissue constituents. "Associations have previously been reported between plasma glycoprotein sialylation and inflammatory states, as well as between ST6GAL1 polymorphisms and autoimmune diseases." (PMID 32391003, 2020). "The increased IgG sialylation resulted from in vivo administration of a soluble ST6GAL1 converted IgG activity into anti-inflammatory in autoimmune disease." (PMID 35370997, 2022). "The sialylation of IgG by ST6GAL1 is necessary for the anti-inflammatory effects of IVIG therapy in autoimmune disease, and variations in serum IgG sialylation have been widely associated with inflammatory diseases." (PMID 31408003, 2019). "Serum ST6GAL1 is also implicated in the sialylation of IgG, enabling binding to inhibitory FcγRIIb, the primary mechanism by which intravenous immunoglobulin (IVIG) alleviates autoimmune disease." (PMID 32391003, 2020). "Moreover, administration of ST6Gal1‐IgG in mice of Goodpasture disease could convert inflammatory IgG into anti‐inflammatory mediator and reduce inflammatory cell infiltration into the kidney and glomerulosclerosis scoring, effectively attenuating autoimmune disease." (PMID 32677771, 2020).
lymph node metastasis (4 papers, 2010 to 2023). "A correlation analysis with clinico-pathological characteristics revealed a significant association (p = 0.017) of ST6GAL1 protein reduction and the existence of lymph node metastasis." (PMID 25465919, 2014). "High ST6GAL1 mRNA levels significantly correlated with lymph node metastasis status, clinical stage, and reduced survival rate." (PMID 38003522, 2023).
lymphoma (4 papers, 2014 to 2026). A malignant (clonal) proliferation of B- lymphocytes or T- lymphocytes which involves the lymph nodes, bone marrow and/or extranodal sites. "Inhibition of ST6Gal1 or GNE activity in lymphoma cells may cause apoptosis, thereby reducing tumor mass or metastatic nodules and enhancing the effects of anticancer drugs." (PMID 31317621, 2019). "Knockdown of beta‐galactoside alpha‐2,6‐sialyltransferase (ST6Gal1) resulted in enhanced lymphoma cell adhesion to galectin‐1 in anaplastic large cell lymphoma cell line, H‐ALCL." (PMID 31317621, 2019). "We speculate that since removal of cell surface sialic acid by knockdown of GNE induces HBL‐8 cell death, oncolysis of lymphoma cells may be induced by neuraminidase treatment or knockdown of ST6Gal1 or GNE." (PMID 31317621, 2019). "This mechanistic model of modulation of cell adhesion to galectin-1 by ST6Gal1 may provide a new concept in understandings the regulatory mechanisms of lymphoma metastasis." (PMID 25573487, 2015). "In our speculation a soluble form of ST6Gal1 may be a regulator to resialylate cell surface of lymphoma cells as indicated in the present results using a recombinant ST6Gal1." (PMID 24589677, 2014). "Therefore, in addition to ST6Gal1, GNE is also a candidate target for lymphoma therapy, especially for the prevention of metastasis." (PMID 31317621, 2019). "There is a clear difference in the desialylation pattern between knockdown of ST6Gal1 and of GNE, but this strategy may provide the same effect on the desialylation of lymphoma cells, resulting in the induction of cell death." (PMID 31317621, 2019).
Obesity (4 papers, 2018 to 2025). Accumulation of substantial excess body fat. "Other BMs revealed to be associated with obesity-related HF are suggestive of mechanisms associated with apoptosis (TNFRSF10A), inflammation (ST6GAL1 and GAL-9) and fibrosis (MMP12, TIMP1 and QPCT)." (PMID 35945262, 2022). "Moreover, epigenetic modifications, such as DNA methylation, regulate ST6GAL1 expression during obesity and represent a potential therapeutic target for modulating adipogenesis." (PMID 41301440, 2025). "Interestingly, hepatic ST6GAL1 deficiency in mice did not exacerbate HFD-induced obesity." (PMID 41301440, 2025).
osteosarcoma (4 papers, 2020 to 2024). A usually aggressive malignant bone-forming mesenchymal neoplasm, predominantly affecting adolescents and young adults. "Similarly, in an osteosarcoma model, loss of ST6Gal1 led to decreased VEGF expression." (PMID 36106023, 2022). "In the MG-63 osteosarcoma cell line, targeting ST6Gal1 decreased expression of N-cadherin, while increasing the expression of E-cadherin." (PMID 36106023, 2022).
anaplastic large cell lymphoma (3 papers, 2019 to 2023). Anaplastic large cell lymphoma (ALCL) is a rare and aggressive peripheral T-cell non-Hodgkin lymphoma, belonging to the group of CD30-positive lymphoproliferative disorders, which affects lymph nodes and extranodal sites. "Studies have revealed that cell adhesion and invasion in Anaplastic Large Cell Lymphoma (ALCL) are regulated by the process of sialylation involving ST6Gal1 and N-glycans." (PMID 36547200, 2022).
asthma (3 papers, 2021 to 2024). "Recently, ST6GAL1 was linked to modulating airway mucins and sialylation levels in asthma, which further altered cell proliferation and inflammation in this disease." (PMID 34290711, 2021). "Interestingly, the role of ST6GAL1 is very relevant in asthma since it plays a critical role in the sialylation of MUC4β in epithelial dysfunction associated with T2-high asthma." (PMID 38785919, 2024). "The levels of ST6GAL1 and sialylated MUC4β have been shown to be increased in airway specimens from patients with T2 asthma, which may cause epithelial dysfunction." (PMID 37256139, 2023). "Mice with a hepatocyte-specific knockout of ST6GAL1 (H-cKO) exhibit significantly increased morbidity due to T cell-dependent HDM-induced asthma." (PMID 37256139, 2023). "In this report, Zhou and colleagues showed that ST6GAL1 regulated airway epithelial cell differentiation and type-2 inflammation in asthma through altered mucin glycosylation and cell proliferation." (PMID 34290711, 2021). "Therefore, ST6GAL1 represents a potential target of a specific sialylation pathway in asthma." (PMID 38785919, 2024).
colorectal tumor (3 papers, 2009 to 2025). "Moreover, ST6GAL1 was found to be upregulated in colorectal tumor samples from our clinical cohort, and its high expression was significantly correlated with poor prognosis in CRC patients, further supporting its oncogenic role." (PMID 40847469, 2025).
IgA nephropathy (3 papers, 2019 to 2024). "Coincident associations at the loci encompassing the C1GALT1 and ST6GAL1 genes contribute to a better understanding of the factors involved in IgA nephropathy (IgAN) risk." (PMID 39123268, 2024). "Human GWAS studies have also associated genetic variation in ST6GAL1 with IgA nephropathy and flucloxacillin-induced liver damage." (PMID 31408003, 2019).
liver cancer (3 papers, 2016 to 2024). An epithelial or non-epithelial malignant neoplasm that arises from the liver. "In liver cancer, ST6GAL1 stimulates progression, and its expression is regulated by miR-9 and by miR-195-3pc/lncRNA TINCR." (PMID 36555445, 2022). "This is the case of liver cancer, in which miR-9 modulates GALNT4 and ST6GAL1, miR-122 modulates FUT8 and GALNT10 and miR-34 modulates ST3GAL5 and FUT8." (PMID 36555445, 2022).